MMP2 (matrix metallopeptidase 2)
Diseases named in the same sentence as MMP2 in open-access papers (continued):
Sharing a sentence is not in itself a finding about the gene and the disease.
tumor (continued). "The present data show that tumour tissue contains higher levels of active and proform MMP-2 and -9 than distant normal mucosa in patients with CRC, with the increase in active MMP-2 being the most pronounced." (PMID 12085179, 2002). "Expression of MMP-2 mRNA in tumour has been described in stromal fibroblastic cells, but MMP-2 protein appears to be localised predominantly in the cytoplasm of tumour cells." (PMID 12085179, 2002). "Transitional tissue and tumour tissue contain similar levels of active MMP-2, -9 and broad-spectrum MMP activity, with the first and latter being significantly higher than those in distant normal mucosa." (PMID 12085179, 2002). "The highlevels of MMP-2 mRNA in MFH indicate a relationship between the proteolytic activity of MMP-2 and the tumor aggressiveness." (PMID 18521441, 2001). "MMP-9, a target of active MMP-2, was present in the metastatic cell line but expression was down-regulated in the tumour cells in vivo, gelatin analysis revealed that MMP-9 was almost entirely attributable to the murine host, confirmed by PCR." (PMID 11401321, 2001). "Matrix metalloproteinase 2 (MMP-2)/gelatinase A plays an important role in tumour invasion and metastasis." (PMID 10376963, 1999). "The expression of MMP-3 correlated to that of MMP-1 (P = 0.03) localized at the tumour mass and stroma of the invasive area, while MMP-2 mRNA was detected widely throughout the stroma independent of MMP-1 expression." (PMID 10362121, 1999). "Since MMP-2 is secreted as an inactive form (proMMP-2) from tumour and neighbouring stroma cells, the activation process is necessary to express the enzymic activity for degradation of extracellular matrix components." (PMID 10376963, 1999). "Additionally, HT downregulates proangiogenic and invasive factors such as TGF-β1, VEGF, and MMP-2/9, contributing to reduced tumor progression." (PMID 41751791, 2026). "MMP‐2 plays a critical role in tumour invasion and metastasis." (PMID 41546170, 2026). "Furthermore, IGF2BP2 deficiency impaired tumor-associated macrophage (TAM)-like polarization in vitro, as evidenced by decreased expression of TAM markers, such as Mrc1, Mmp2, and Il10." (PMID 41943844, 2026). "Correspondingly, tumor-associated target genes including ALDH3A2, SEMA3F, MAP4K5, and TRIP13 were upregulated, whereas PIK3IP1, AGO2, MMP2, and RALBP1 were suppressed." (PMID 41897301, 2026). "Furthermore, we examined the expression of MMP2/MMP9 in in vivo experiments, which showed that the expression levels of MMP2/MMP9 proteins in the tumor of the shRNA-HIF-1α group were decreased compared to the shRNA-NC group." (PMID 39781344, 2025). "This suggests that while MMP2 may promote invasion and metastasis, it also influences other aspects of tumor cell behavior." (PMID 39833941, 2025). "After accumulation in tumor tissues via the enhanced permeability and retention effect, the outer shell of PEG is removed by matrix metalloproteinase-2 (MMP-2) overexpression in the tumor microenvironment, thereby exposing phospholipid bilayers and facilitating cellular internalization." (PMID 40693277, 2025). "Also, MMP-3 was more expressed in tumor stroma at diagnosis when compared to healthy stroma, and MMP-2 was more expressed in T cell tumors compared to B cell tumors at diagnosis." (PMID 40427122, 2025). "HSP90 is secreted by tumor cells, interacting with MMP-2 and MMP-9." (PMID 41369386, 2025). "ABX-IL8, functioning as a neutralizing antibody against CXCL8, can significantly inhibit the promoter activity and collagenase activity of MMP2 in melanoma cells, thereby diminishing tumor metastasis, reducing tumor angiogenesis, and augmenting tumor apoptosis." (PMID 39925807, 2025). "In such cases, combining MMP-2 inhibition with PD-L1 blockade may help to recruit more TILs into the tumor bed, thereby remodeling the immune microenvironment and reducing resistance to immunotherapy." (PMID 40611940, 2025).
tumor (continued). "Additionally, apigenin inhibits metastasis by down-regulating proteins involved in EMT and tumor cell invasion, such as Snail1, MMP-2, and MMP-9." (PMID 40490812, 2025). "The presence of MMP-2 has also been implicated in the initiation of new blood vessel formation, as tumors expressing MMP-2 tend to have a higher number of capillaries at the interface with tumor cells." (PMID 41179937, 2025). "In addition, STAT3 contributes to tumor cell invasion by upregulating matrix-degrading enzymes such as MMP-2 and MMP-9." (PMID 40723906, 2025). "Additionally, MMP2 releases various pro-angiogenic factors, which contribute to the blood supply needed for tumor growth." (PMID 40303286, 2025). "Matrix metalloproteinase 2 (MMP2) is required for VM of tumor cells." (PMID 40615663, 2025). "M2 TAMs promote tumor progression by expressing PD-L1, remodeling the extracellular matrix through matrix metalloproteinases (MMP2, MMP9), enhancing angiogenesis via vascular endothelial growth factor (VEGF), and recruiting immunosuppressive cells such as Tregs." (PMID 40475782, 2025). "Targeting MMP-2 may serve as a promising treatment strategy to potentiate the efficacy of anti-PD-L1 therapy by modulating the tumor immune microenvironment in COAD." (PMID 40611940, 2025). "This suggests that MMP-2 may play a distinct and possibly less critical role in SP-mediated tumor biology compared to MMP-9." (PMID 40321254, 2025). "Given that MMP-2 is known to promote tumour invasion and metastasis, this discovery is noteworthy." (PMID 40217305, 2025). "Moreover, MMP9, together with MMP2 mediates tumor cells’ invasion through degradation of collagen IV." (PMID 41383620, 2025). "In contrast, MMP-2 demonstrated a more robust increase exceeding two-fold, which is more likely to represent meaningful transcriptional reprogramming with functional consequences for tumor invasiveness and extracellular matrix remodeling." (PMID 41401147, 2025). "Moreover, BEZ-235 has been shown to inhibit PI3K/mTOR-dependent signaling nodes such as AKT, S6, and 4EBP1, reducing MMP-2 expression and invasive migration across multiple tumor types." (PMID 40869090, 2025). "However, emerging evidence indicates that MMP-2 is also involved in shaping the tumor immune microenvironment, thereby influencing immune evasion mechanisms, including those mediated by PD-L1." (PMID 40611940, 2025). "Additionally, TFPI-2 blocked PSAP-induced enhancement of matrix metalloproteinase-2 (MMP-2) activity, which is closely linked to tumor cell invasive/migratory capabilities." (PMID 40801564, 2025). "Additionally, the effects of tumor microenvironmental pH (~6.5) and MMP-2 concentration on drug release dynamics were investigated." (PMID 40732329, 2025). "MMP-2 activity was strongly correlated with tumor invasiveness (r2 = 0.95) and could be inhibited by metalloprotease inhibitors or protein kinase C (PKC) inhibition via calphostin C, reducing invasion by >90%." (PMID 40265458, 2025). "MT-MMP, a potent activator of MMP-2, shows the same expression pattern as that of MMP-2 and may condition tumour invasiveness." (PMID 40724562, 2025). "MMP-2 can also interact with tumour and endothelial cells via the αVβ3 integrin." (PMID 40724562, 2025). "Additionally, elevated levels of MMP2 and MMP9 are associated with worse prognosis, greater lymph node dissemination and increased tumour aggressiveness." (PMID 40259907, 2025). "The strong inverse correlation between ZNF24 and MMP2 expression was observed in vitro and in vivo, suggesting that ZNF24 may be a potential tumor suppressor that may negatively regulate MMP2 expression in CRC." (PMID 40520987, 2025). "For example, DDR1 modulates the MMP and chemokine secretion to recruit macrophages, shaping an immunosuppressive TME, a mechanism validated in hepatic metastasis models where DDR1 silencing reduces MMP2/9 and prometastatic factors in HSCs, thereby inhibiting tumor growth and immune escape." (PMID 41394854, 2025).
tumor (continued). "Additionally, the expression of matrix metalloproteinase-2 (MMP-2), a key marker of tumor invasion and metastasis, was reduced with increasing concentrations of faberidilactone A." (PMID 40076318, 2025). "The combination of MMP-2 inhibitors with PD-L1 blockade could represent a novel therapeutic strategy for overcoming resistance to monotherapy and enhancing anti-tumor immunity in COAD." (PMID 40611940, 2025). "Given the well‐characterised roles of MMP2 and MMP9 in extracellular matrix degradation and metastatic dissemination, their suppression suggests a mechanistic link between PTGER4 deficiency and impaired tumour invasiveness." (PMID 41284374, 2025). "Notably, genes associated with metastasis, such as MMP2 and FAP, were upregulated in TRPM8 KO samples, indicating a potential role for TRPM8 in inhibiting tumor invasion." (PMID 40214455, 2025). "Additionally, T2Dexo-PDOs exhibited enhanced extracellular matrix remodeling with heightened interactions involving MMPs (e.g., MMP2—([TGAV + ITGB3]) crucial for tumor cell invasion and migration." (PMID 40858992, 2025). "MMP2 and MMP9 are invasion-associated gelatinases responsible for extracellular matrix degradation and subsequent tissue invasion, and they have been described with elevated expression in canine neoplasms." (PMID 40509054, 2025). "Moreover, IHC analysis revealed reduced staining for ZDHHC15, MMP‐2, and CYR61in tumor sections from animals receiving ZDHHC15‐depleted tumor cells." (PMID 39686664, 2025). "Moreover, MMP2 was overexpressed in the early and late stages of tumor progression in the stromal area, and CXCR4 and CXCL12 were enriched after mid-stage progression inside the tumor." (PMID 39965034, 2025). "In addition, MMP-2 causes TH2 polarisation of macrophages from the TH1 subtype, therefore restricting the anti-tumour immune response." (PMID 41373503, 2025). "The proteoglycans in the cancer pathway also show significant involvement, with 10 genes and an FDR of 1.75 × 10−6, encompassing genes such as MMP2, FGF2, and PKAc, which are associated with extracellular matrix remodelling and tumour microenvironment regulation." (PMID 40699738, 2025). "In this study, our results indicated that MMP-2 high expression is negatively correlative with TILs, which may hinder the infiltration of these TILs into the tumor microenvironment, thereby driving immune escape and tumor progression." (PMID 40611940, 2025). "After release from the gel, Gelatinase-cleavable peptide Pro-Val-Gly-Leu-Iso-Gly (PVGLIG) can be degraded by MMP2/9 in tumor tissue, which induced the aggregation of NPs, effectively taken up by cancer cells, improved GA concentration in tumor cells and enhanced the antitumor effect of GA." (PMID 40104652, 2025). "Notably, TRL treatment enhanced the tumor’s response to Gemcitabine by decreasing collagen and MMP2 levels while simultaneously increasing L1CAM expression." (PMID 40770187, 2025). "Co-expression of CD44v6 and MMP2 correlates with tumor progression and metastasis." (PMID 40363706, 2025). "The cleavage of the laminin 5 g2-chain by MMP2 into laminin 5 g2’ and g2x pro-migratory fragments could induce a vasculogenic phenotype in poorly aggressive tumor cells, resulting in the formation of VM." (PMID 40615663, 2025). "MMP2 secreted and activated by MB cells can degrade collagen IV surrounding tumors and the basement membrane, resulting in the invasion of MB cells into nearby tissues, followed by tumor growth and spread through capillary endothelium and neovascularization." (PMID 40785845, 2025). "The direct activation of MMP-2 by HSP90 increases tumor cell motility and invasiveness." (PMID 41369386, 2025). "Furthermore, in each model, IHC staining of tumor sections from mice fed with a PA diet had increased staining for MMP‐2, YAP, and ZDHHC15 compared to mice fed with an Olive‐diet." (PMID 39686664, 2025).
tumor (continued). "The overexpression of MMP-2 and MMP-9 has been associated with advanced tumor-node-metastasis (TNM) staging because they play a role in promoting metastasis, invasion and poor differentiation of tumor cells." (PMID 39057397, 2024). "Moreover, they promote adhesion and invasion of tumour cells by producing matrix metalloproteinase-2 (MMP-2), before becoming essential components of the tumour stroma in newly-formed metastases." (PMID 38783165, 2024). "In addition, the treatment also enhanced the inhibitory effect of cisplatin on tumor recurrence and eliminated the cisplatin-induced upregulation of MMP-2." (PMID 39335164, 2024). "Regarding the link between MMP-2 and tumor grade, the results are conflicting." (PMID 38248804, 2024). "MMP-2 is secreted by both neuroblastic tumor cells as well as stromal cells." (PMID 38884093, 2024). "As a downstream target of FCRLA, MMP2 may provide valuable insights into the regulation of the RCC tumor microenvironment." (PMID 39108036, 2024). "It is worth noting that miR-125b-5p is a vital suppressor miRNA that can target peroxiredoxins like 2 A (PRXL2A), signal transducer and activator of transcription 3 (STAT3), matrix metalloproteinase-2 (MMP2), and others to induce tumor cell death or increase drug sensitivity." (PMID 39223142, 2024). "Immunohistochemical staining also revealed decreased MMP-2 expression in tumor tissue." (PMID 39335164, 2024). "The inhibition of MMP2/MMP9 by SB-3CT prolongs survival time by promoting anti-tumor immunity." (PMID 38375034, 2024). "In a study on solid ovarian cancer samples, peritoneal metastasis-associated fibroblasts and fibroblasts from primary tumour expressed increased levels of collagen and ECM-remodelling proteins (MMP2/11), when compared to fibroblasts from normal adjacent tissue." (PMID 38783165, 2024). "The addition of IL-1RA during co-culture significantly inhibited the activation of both MMP-2 and MMP-9 in SUM159 cells and suppressed MMP-2 activity in MCF12A cells These results underscore the role of IL-1β signaling in promoting tumor cell invasiveness and MMP activation in TNBC." (PMID 39801513, 2024). "TAMs respond to hypoxic conditions within tumor tissue by secreting various factors, including VEGFs, basic fibroblast growth factor (bFGF), thymidine phosphorylase, and multiple matrix metalloproteinases (MMPs), such as MMP-2, MMP-7, MMP-9, and MMP-12." (PMID 39404428, 2024). "Notably, studies involving mice deficient in MMP2 or MMP9 have underscored their essential role in promoting colonization and tumor proliferation." (PMID 38939095, 2024). "The immunohistochemical staining of MMP‐2 and H&E results of the xenografted tumor tissues showed that collagen and FN treatment could better promote matrix remodeling and micro‐vessel formation." (PMID 39036079, 2024). "Matrix metalloproteinase 2 (MMP2) is crucial in tumor-mediated extracellular matrix degradation." (PMID 39228402, 2024). "Interestingly, research has found that Tregs inhibit the production of MMP2 in the early stages of tumor development to control the invasion and migration processes, possibly related to the dual nature of Tregs." (PMID 38690275, 2024). "Therefore, we explored some important EMT-related genes both in the adjacent tissues and tumor tissues, including matrix metallopeptidase 2 (MMP2), N-cadherin, and E-cadherin." (PMID 38271114, 2024). "Moreover, the levels of proteins involved in cell proliferation (p-Stat3, PCNA, Ki67, and cyclin D1) and cell migration (MMP2) were analyzed in the tumor tissues." (PMID 38441416, 2024). "have shown that MMP2 is a reliable predictor of tumor progression and metastasis." (PMID 39850819, 2024). "Second, pJNK and MMP2 can also promote tumor invasion and migration in other malignancies, and it may thus be necessary to search for LRP1–SNRNP25-specific downstream signaling molecules." (PMID 38678020, 2024).
tumor (continued). "Moreover, CAFs contribute to tumor proliferation by secreting matrix-metalloproteinases (MMPs), including MMP-2, MMP-3, MMP-9, and MMP-13." (PMID 39338413, 2024). "In addition, decreased expression of vimentin, Twist, MMP-2 and MMP-9 is associated with inhibition of tumor growth, cell migration, invasion and cancer metastasis and increased sensitivity to chemotherapeutic agents." (PMID 38737746, 2024). "MMP2 expression was less in the tumor in comparison to the corresponding surroundings." (PMID 39132498, 2024). "METABRIC miR-18a/low tumours displayed elevated levels of MMP2 (p < 0.05)." (PMID 38786043, 2024). "Targeting MMP2 can improve the tumor microenvironment and enhance sensitivity to immunotherapy." (PMID 38690275, 2024). "For example, TGF-β, FGF2, EGF, and interleukin 6 (IL-6) stimulate cancer cell proliferation; VEGF and platelet-derived growth factor (PDGF) promote angiogenesis; MMP-2 and MMP-9 degrade extracellular stroma; and CCL22 recruits Tregs lymphocytes to cause tumour immunosuppression." (PMID 39337393, 2024). "Similarly, Interleukin 33 (IL-33) is secreted by CAFs during tumor progression but has also been found to enhance HNSCC invasion through MMP2/9 mediated ECM degradation." (PMID 38942893, 2024). "Similarly, small molecule inhibitors targeting MMP2/9 can increase antitumor immunity, reduce tumor burden, and extend patient survival." (PMID 38693104, 2024). "Their hypothesis was that this could be due to a greater secretion of proteases (such as MMP2) which degrade VN upon tumor progression." (PMID 39201421, 2024). "Among these enzymes, MMP2 play a critical role in tumor metastasis and invasion." (PMID 39598564, 2024). "Furthermore, MMP-2 overexpression triggered the in situ release of αPD-L1 in the tumor, preventing tumor cells from evading CTL-mediated killing." (PMID 38690275, 2024). "Interestingly, recent preclinical investigations have identified the natural compound, chlorotoxin, as a novel antigen which exhibits preferential binding to GBM tumours compared to normal brain tissues, mediated by the expression of MMP-2 on tumour cells." (PMID 38615034, 2024). "Additionally, the results show a robust antimigratory effect of GATPP+C10 and TPP+C10, reducing the activation pathways linked to tumor progression and reducing the expression of VEGF and MMP-2 and MMP-9, common biomarkers of advanced CRC." (PMID 39272835, 2024). "Matrix metallopeptidase 2 (MMP2) is a zinc‐related proteinase involved in tumor metastasis." (PMID 39108036, 2024). "MMP2 is a ubiquitin metalloproteinase involved in various biological functions in the human body, such as vascular system remodeling, angiogenesis, tissue repair, tumor infiltration, inflammation, and atherosclerotic plaque rupture." (PMID 39568012, 2024). "In addition, circFKBP8 silencing significantly inhibited the protein levels of E2F7, KI-67, MMP2 and Nanog in tumor tissues." (PMID 39192374, 2024). "Glabridin reduces MMP-2 secretion, limiting tumor cell degradation of the ECM." (PMID 39723390, 2024). "Suppression of fibronectin, vimentin, N-cadherin, MMP-9, MMP-2, twist, and snail.↑ Epithelial markers E-cadherin and Occludin levels.↓ Migratory and invasive potential of tumor cells by reversing epithelial-to-mesenchymal transition (EMT). ↓ PI3K/Akt/mTOR activation." (PMID 38611719, 2024). "Therefore, elevated MMP-2 levels in tumor tissues have been used to activate drug release in many studies." (PMID 39125066, 2024). "The ERK/MMP2 pathway is one of the key triggers of tumor cell migration in human cancers." (PMID 38311733, 2024).